RB1 (RB transcriptional corepressor 1)
Diseases named in the same sentence as RB1 in open-access papers (continued):
Sharing a sentence is not in itself a finding about the gene and the disease.
cancer (continued). "It should be noted that, according to the information reported by the cBioPortal for cancer genomics, the human RB1 gene, as well as the genes encoding CDK4 (CDK4), CDK6 (CDK6), and cyclin D1 (CCND1), are all expressed in AGS and MCF-7 cells, without mutations reported so far." (PMID 37298236, 2023). "The loss of RB1 gene function through mutation or other mechanisms leads to retinoblastoma, rare cancer that is the primary type of ocular neoplasia in children and is also found in small cell cancer of the lung, endometrial cancer, bladder cancer, and osteogenic sarcoma." (PMID 37509254, 2023). "In addition to increased risk for Rb development, individuals with constitutional mutation of Rb1 also have a predisposition to secondary cancers in other tissues." (PMID 36177499, 2023). "RB1 is a tumor suppressor gene that is mutated in several types of cancer." (PMID 37202799, 2023). "LOI of KvDMR1, INPP5Fv2-DMR and RB1-DMR is also implicated in the pathogenesis of cancer." (PMID 36866275, 2023). "Indeed, RB1 inactivation has been linked to cancer initiation and progression and resistance to several targeted therapies, including androgen receptor (AR) antagonists, ER antagonists, CDK4/6 inhibitors, and EGFR tyrosine kinase inhibitors." (PMID 36928314, 2023). "Among paralogues, RB1 loss of function alterations are more broadly observed across human cancer." (PMID 35368709, 2022). "Furthermore, a recent study also showed that high-risk HPV infections went together with mutations in PIK3CA, EP300, NF1, and RB1 in samples from benign tonsils, suggesting these mutations to be potential biomarkers to identify the cancer progression risk." (PMID 35887235, 2022). "RB1 is significantly associated with metastasis of various cancer." (PMID 35969010, 2022). "This cancer is associated with high (85–95%) penetrance RB1 gene alterations." (PMID 35406801, 2022). "From a pan-cancer perspective, although the bi-allelic deletion of RB1 is relatively uncommon, some aspects of non-canonical pathways, e.g., DNA damage repair, appear to be sensitive to single-copy RB1 loss." (PMID 35406559, 2022). "In retinal cells, RB1 gene loss promotes various epigenetic events including DNA methylation and microRNA regulation all of which ultimately culminate in the dysregulation of diverse oncogenic and tumor suppressor proteins that favor cancer pathogenesis." (PMID 35359459, 2022). "RB1 loss of function is involved in the development of other cancers as well." (PMID 35368709, 2022). "After whole exome analysis is carried out on the patient with the shortest response, we observed the appearance of RB1 loss-of-function mutation that could be a mechanism of resistance to MEK inhibitors in RAS- of RAF-mutated cancers." (PMID 35328764, 2022). "Analysis of mutation types and frequencies in patient-derived cancer samples deposited in the cBio Cancer Genomics Portal (cbioportal.org; accessed on 8 February 2022) database revealed that Rb1 is altered (point mutations, deletion, amplification) in 7% of all samples." (PMID 35267571, 2022). "It is unclear whether loss of other pocket protein paralogues will phenocopy loss of RB1 in the context of cancer lineage plasticity and therapeutic resistance as systematic comparisons are lacking in the published literature." (PMID 35368709, 2022).
cancer (continued). "Importantly, RB1 loss increases opportunities for mutation of several cancer driver genes, most notably the TERT gene, which plays critical roles in carcinogenesis by sustaining proliferative capacity." (PMID 34983823, 2022). "Inactivation of RB1 functions and the RB pathway is a major hallmark of cancer." (PMID 34359636, 2021). "In addition, the decision to treat with EBRT carries a risk of iatrogenic second malignant neoplasms among patients with a germline RB1 mutation, and so many centers choose enucleation over salvage radiotherapy." (PMID 34066325, 2021). "Since PARPi hypersensitivity in cancers is caused by BRCAness/ HRd29, we determined if RB1 loss may yield BRCAness/ HRd." (PMID 34862364, 2021). "In summary, we identified several high confidence, evolutionarily conserved, novel targets for RB1-deficient cells that may be further adapted for the treatment of human cancer." (PMID 33591981, 2021). "In summary, our results suggest that many of the genes found to be SL partners of RB1 in the Drosophila screen and human cancer cell lines may also be associated with survival outcomes in human patients whose tumors have lost RB1 expression." (PMID 33591981, 2021). "In addition, we found that Retinoblastoma (RB1) was frequently mutated in multiple cancer types, such as BLCA and SKCM." (PMID 34429404, 2021). "Finally, this review will discuss putative approaches to treat RB1-deficient cancers by targeting comparatively large-scale chromosomal aberration involving the RB1 loci." (PMID 34359636, 2021). "Nonsense mutations that are predicted to be pathogenic and cancer-related in ClinVar are in RB1 in UM-MCC9 (rs794727481) and UM-MCC34 (rs121913304), in BAP1 in UM-MCC32 (chr3.52437267.G > A), and in the tumor-suppressor gene CHEK2 in MKL-1 (chr22.29091725.C > T)." (PMID 33562873, 2021). "In addition, carriage of a low penetrance mutation in the RB1 gene increases the risk of developing other malignant neoplasms in various locations throughout life." (PMID 34680218, 2021). "E2F activity, as defined by expression of E2F target genes, is high in virtually all cancers, often owing to inactivation of its main binding partner and key regulator, RB (encoded by RB1), overexpression of cyclin-dependent kinases (CDKs) or inactivation of CDK inhibitors." (PMID 34778082, 2021). "We next assessed whether human orthologs of the hits identified in our Drosophila screen were also SL with RB1 loss in human cancer cell lines." (PMID 33591981, 2021). "We chose to test whether 11 genes that serve as potential therapeutic targets for RB1-deficient cancer cells in different settings can also suppress the growth of tumors with additional alterations." (PMID 33591981, 2021). "In addition, RB1 mutations have been shown to sensitize cancer cells to the mitotic inhibitors Taxol and STLC." (PMID 33591981, 2021). "In addition, Aurora A kinase inhibitor LY3295668, Aurora B kinase inhibitor AZD2811, the mitotic inhibitors Taxol and STLC, and a SKP2 inhibitor were all shown to be more selective against RB1-deficient cancer cells." (PMID 33591981, 2021). "The importance of the biallelic loss of RB1 is an example of Knudson’s “two-hit” hypothesis of cancer." (PMID 33466343, 2021). "Interestingly, increased E2F activity is an expected feature of SCLC due to the recurrent loss of the negative regulator RB1 in this cancer; and we were able to confirm this phenotype in our own RB1 knockdown models." (PMID 33084222, 2021).
cancer (continued). "Five (11.0%) had pathogenic germline mutations in other non-RB1 cancer predisposition genes." (PMID 33466343, 2021). "The retinal organoids made deficient for RB1 may provide a model to examine the initiation and development of tumors, such as the cancer cell-of-origin." (PMID 32824373, 2020). "RB1 mutations are found in a variety of cancer at variable frequencies." (PMID 33037191, 2020). "Therefore, the genetic instability characteristic of cancer would inactivate the inserted RB1 allele." (PMID 33297561, 2020). "Together, this suggests that using MLN4924 to inhibit SKP2 could be effective in other RB1 deficient cancers." (PMID 32123578, 2020). "On the other hand, the loss of RB1, a tumor suppressor gene, is common in many cancers." (PMID 32825052, 2020). "This study shows that stathmin-mediated disruption of microtubule dynamics is critical to induce synthetic lethality in RB1-deficient cancer and suggests that upstream factors regulating microtubule dynamics, such as AURKA, can be potential therapeutic targets in RB1-deficient cancer." (PMID 33037191, 2020). "RB1 deficiency is connected with cancer invasion and metastasis." (PMID 33489906, 2020). "Hence, alterations in RB1 can cause genomic instability, thereby fostering an accumulation of mutations and providing an evolutionary advantage to the affected cancer cells." (PMID 31038669, 2019). "Therefore, in this study, we confirmed that Rbfox2 dissociation from RB1 mRNA associated with SGs following resveratrol treatment inhibited cancer progression." (PMID 31028247, 2019). "If the LoF variant is located in a tumour suppressor (Ts) gene, it is likely to result in haploinsufficiency of that Ts gene, irrespective whether it is present in the last exon, which is a hallmark for cancer (with some exceptions like RB1)." (PMID 31888289, 2019). "In addition, ULM with bizarre nuclei are quite rare and the RB1 gene is often mutated in a wide range of cancers." (PMID 31387281, 2019). "Interestingly, a recent study identified a pan-cancer transcriptomic signature for predicting RB1 loss, using validated data sets from The Cancer Genome Atlas (TCGA) and Pan-Cancer." (PMID 31366128, 2019). "Moreover, the loss of Rb1 has profound effects on many other cellular processes relevant to cancer, including differentiation." (PMID 31068575, 2019). "In addition, RB1 mutations are also significantly associated with reduced cancer-specific and recurrence-free survival after resection in HCC patients." (PMID 30521023, 2018). "RB1 deficiency makes cancer cells resistant to CDK4/6 inhibitors, but may also prevent efficient PARP1 gene targeting." (PMID 29306194, 2018). "Based on the genetic make-up of the individual, there are three major scenarios where an RB Patient would require lifelong follow-up for future family planning or to avoid any risk of secondary cancers: 1) germline RB1 mutations, 2) germline RB1 Mosaicism, or 3) low penetrance RB1 Mutations." (PMID 28575107, 2017). "Interestingly, preclinical and clinical evidence in multiple cancer types suggest that RB1 expressional loss is associated with increased responsiveness to conventional chemotherapies." (PMID 28390395, 2017).
cancer (continued). "RB1 mutations were associated with cancer recurrence in resectable HCCs." (PMID 26943571, 2016). "Different approaches exploiting RB1 loss to kill cancer cells have been designed." (PMID 26160835, 2015). "For example, germline mutations in RB1 predispose an individual to a very limited set of cancers." (PMID 25755634, 2015). "For RB1, its methylated status was strongly associated with cancer (p = 0.009)." (PMID 26032781, 2015). "Previous studies have shown that genes associated with the RB1/E2F pathway are commonly deregulated in many human cancers via genetic or epigenetic mechanisms, resulting in the activation of E2F and leading to the transcription of several genes that regulate cell growth." (PMID 26317630, 2015). "RB1 methylated status was associated with cancer (p = 0.009) and HPV infection (p = 0.042)." (PMID 26032781, 2015). "An Rb1 mutation is associated with the development of certain types of cancer." (PMID 26467212, 2015). "Heritable mutations in the RB1 encoding gene greatly increase the risk for development of the paediatric eye tumour retinoblastoma and significantly enhance the overall lifetime risk for the development of other cancers." (PMID 23516486, 2013). "The hypothesis was confirmed in 1986 when RB1 became the first cancer susceptibility gene identified in humans." (PMID 22550413, 2012). "This may offer some insight into why the RB1 gene is mutated in cancer, but the RBL2 gene (encoding p130) is generally spared." (PMID 22417103, 2012). "In addition, the cancer-causing missense mutations in RB-1 that have been described are found mostly within the large pocket and this has focused efforts most intensively on this domain." (PMID 17854503, 2007). "The investigation of endogenous pRB protein complex composition, combined with structure-function analysis of discrete mutant alleles of the RB-1 gene, offers a logical means to separate pRB function into distinct parts to define its role in cancer." (PMID 17854503, 2007). "The discovery that RB1 is a gene whose mutations can also predispose a person to sarcomas, which in turn can be initiated by ionizing radiation, has implications for other cancers, and pediatrics has led the way in modifying therapy to reduce the probability of such a consequence." (PMID 16231982, 2005). "However, RB1 was rarely considered as a direct therapeutic target for drug screening and strategy design due to the fact that the dominant truncating mutations and CN deletions of RB1 in cancer render it untargetable." (PMID 40904703, 2025). "Because RBness shared the transcriptional profile of RB1-defective cancers and was associated with aggressive forms of cancer, we next asked whether these cancers shared therapeutic vulnerabilities with RB1-defective cancers that could be exploited for designing targeted therapies." (PMID 40138429, 2025). "Furthermore, patients with germline RB1 pathogenic variants are not only at higher risk of bilateral ocular disease but also at an increased risk of additional malignant neoplasms throughout their lives that are associated with significant morbidity and mortality." (PMID 39724000, 2024).
cancer (continued). "Integrating multi-omics approaches, including genomics, transcriptomics, proteomics, and metabolomics, could further enhance our understanding of RB1-deficient cancers and facilitate the development of personalized treatment strategies tailored to individual patients’ molecular profiles." (PMID 38672640, 2024). "Therefore, by increasing ACSL4 expression and the rate of lipid peroxidation, RB1 loss raises the extent that cancer cells depend on GPX4 to block ferroptosis and, on the other hand, sensitizes cancer cells to GPX4 inhibitors or, in general, ferroptosis inducers." (PMID 37183818, 2023). "Resulting RB1 loss driven cancer lineage plasticity may facilitate adaptation of cancer cells to selective pressures experienced during metastatic dissemination and therapy, thereby driving cancer progression." (PMID 35368709, 2022). "Therefore, whilst the loss of RB1 function is recognized as a hallmark of an overall poor prognosis for cancer patients, it may paradoxically provide clinically important vulnerabilities that could be targeted by genotoxic agents." (PMID 34359636, 2021). "The same group estimated variants in one of 156 cancer predisposition genes among 2450 adult CCSs using whole-genome sequencing, with 11.8% of them carrying a pathogenic/likely pathogenic variant, and they frequently detected variants of Rb1, NF1, and BRCA2 genes." (PMID 34680213, 2021). "Moreover, AURKA inhibition has synthetic lethality in cancer cells possessing RB1 mutation." (PMID 34359608, 2021). "Recent surveys of cancer genome landscapes have shown that alterations of a particular pathway can involve many different genes and many different kinds of disruptions—for example, RB1 mutation, RB1 methylation, or CDKN2A deletion can all lead to aberrant cell proliferation." (PMID 33861732, 2021). "Since RB1 function can clearly be compromised by multiple events in addition to direct genetic loss in human cancers (e.g., HPV-E7 or CDK4/6 activity), we focused on developing a transcriptional tool to evaluate RB activity based on transcription that could be broadly deployed across tumors." (PMID 32242058, 2020). "Interestingly, alterations of both Cx43 and RB1 seem to be associated with cancer development." (PMID 32164318, 2020). "However, as RB1-loss is typically found in neuroendocrine marker expressing SCLC this might point to the associated DLL3-expression in this set of carcinomas." (PMID 31109352, 2019). "Our study showed higher mutation load in patients carrying ATM/RB1 mutations in the combined datasets, suggesting the correlation between DNA repair defect and mutation burden may still be present in sporadic cancers as a result of increased genomic instability through loss of DSB DNA repair." (PMID 29682192, 2018). "Moreover, the majority of human cancers have either mutations in the RB1 gene, or mutations in other genes in the RB pathway that result in a functionally inactivated RB, such as increased expression of cyclin D, CDK4 or CDK6 or silencing of the CDK inhibitor p16." (PMID 28812991, 2017). "RB represents one of the rare cancers in which the initiating genetic lesion (RB1 loss of function) is known, and provides an excellent system in which to identify new genes, which may, like RB1, have broad importance for cancer development." (PMID 23233862, 2012). "Based on these data we hypothesized that cancer derived mutant alleles of human RB1 in these three exons have the potential to specifically disrupt LXCXE-type interactions in isolation from other interactions with pRB's pocket domain." (PMID 20298605, 2010).